LCN2 (lipocalin 2)
Diseases named in the same sentence as LCN2 in open-access papers (continued):
Sharing a sentence is not in itself a finding about the gene and the disease.
tumor (continued). "Collectively, these results suggest that LCN2 deletion induces SAA1 hypoactivation, which is assumed to lead to tumor angiogenesis in GC based on the role of SAA1 polymorphisms." (PMID 35705840, 2022). "Recently it was described elevated expression of LCN2 in inflammatory breast carcinoma which advanced tumor growth, skin invasion, and metastasis." (PMID 36077676, 2022). "To validate these findings in vivo, we implanted control, CLDN1 and LCN2 depleted cells into the mammary fat pad of obese and lean mice and assessed tumor formation." (PMID 35013251, 2022). "In these mice, the lack of LCN2 caused a significant reduction in immune cell infiltration, PanIN, and tumor growth, suggesting that LCN2 in the TME is an important determinant for PDAC progression and patient prognosis, similar to MMP-9." (PMID 35216088, 2022). "According to previous findings, low expression of ATM, TAP1 and LCN2 will increase the sensitivity of tumor cells to cisplatin, which is the same as our study conclusion and further illustrates the accuracy of our method." (PMID 36016575, 2022). "LCN2 has also been correlated with poor prognostic factors such as high histological grade, ER and PR negativity, tumor relapse, as well as poor patient survival." (PMID 36077676, 2022). "A recent study showed that a high expression of LCN2 was shown in NPC patients with a better prognosis using an immunohistochemical analysis of LCN2 tumor specimens." (PMID 36428800, 2022). "This evidence was corroborated by the opposite trend observed in the LGG tumor showing downregulation of LCN2 and MMP9 along with hypermethylation of the promoter region." (PMID 36211450, 2022). "Combined, these results suggest that CLDN1 and LCN2 are the downstream mediators of C/EBPB induced tumor formation capacity in the obese setting." (PMID 35013251, 2022). "Overexpressing LCN2 in vivo also promoted tumor growth via enhanced AR transcriptional activity in C4-2B and 22Rv1 cells." (PMID 35406450, 2022). "Our study provides mechanistic details to better understand tumor pro-survival pathways initiated by iron-loaded Lcn-2." (PMID 34069743, 2021). "We also checked the amount of iron-loaded Lcn-2 in ccRCC tumor tissues compared to adjacent healthy tissues." (PMID 34069743, 2021). "Along the same line, we did not observe any significant differences regarding the total mRNA expression of FPN and Lcn-2 in whole tumor homogenates from wildtype PyMT mice compared to healthy murine breast tissue." (PMID 33808732, 2021). "To evaluate the effect of EC fluids from either WT or Lcn-2−/− tumors on the cellular proliferation and migration of primary WT PyMT tumor cells, we applied the xCELLigence real-time measurement system." (PMID 33808732, 2021). "After KPC tumor implantation, we observed increased food consumption in Lcn2-KO mice relative to wild-type (WT) control." (PMID 33824339, 2021). "The observed reduction in the number of colonies upon LCN2 silencing suggests that LCN2 promotes the self-renewal capacity of IBC tumor cells." (PMID 34445288, 2021). "We further identified iron-loaded Lcn-2 in extracellular tumor fluids, which, in turn, favored tumor proliferation, matrix adhesion, and migration of tumor cells in vitro." (PMID 33808732, 2021). "On the other hand, iron-loaded Lcn-2, which comes from other sources within the tumor microenvironment, adds to the protective effects by inducing antioxidant pathways." (PMID 34069743, 2021). "In some studies, contradictory results have been reported for the association between some clinicopathologic parameters such as tumor differentiation, tumor stage, and lymph node metastasis and lipocalin-2 expression." (PMID 33542838, 2021). "Elevated LCN2 expression has been shown to lead to increased invasion, tumor formation, and metastasis in different tumor types." (PMID 35008796, 2021).
tumor (continued). "We demonstrated that silencing of LCN2 reduced tumor initiation and growth, skin invasion/recurrence, and brain metastasis burden in preclinical mouse models of IBC." (PMID 34342930, 2021). "Our own unpublished observations point to the role of Lcn-2-depedendent signaling in promoting cellular stress mechanisms, which, in turn, favor therapy resistance, and thus, tumor growth." (PMID 33808732, 2021). "scRNAseq analysis done on tumor cells isolated from the leptomeninges of patients with metastatic growth showed high expression of the iron-binding protein lipocalin-2 (Lcn2) its receptor SLC22A17." (PMID 34276313, 2021). "Downstream signalling of p38β also leads to an increase in expression of the oncogene, Lipocalin2 (LCN2), and an increase in tumour cell migration." (PMID 34174910, 2021). "We observed higher levels of both FPN (left) and Lcn-2 (left) mRNA expression in tumor MΦ compared to their healthy counterparts." (PMID 33808732, 2021). "Considering the proposed role of Lcn-2 for the availability of iron within the tumor, we determined the overall iron amount in tumors from wildtype (WT) and Lcn-2−/− PyMT mice." (PMID 33808732, 2021). "Similar to the Lcn2-KO tumor-bearing mice, AgRP-treated mice had improved skeletal and cardiac tissue mass at the end of the study." (PMID 33824339, 2021). "We further demonstrate, with in vitro and in vivo studies, that LCN2 has a tumor promoter function in IBC." (PMID 34342930, 2021). "The tumor microenvironment controls the LCN2 function through autocrine system of cancer cells via endoplasmic reticulum stress-dependent and independent mechanisms." (PMID 34072157, 2021). "Similar to Lcn2-KO tumor-bearing mice, AgRP-treated mice demonstrated a significant improvement in food intake and modest improvements in muscle mass." (PMID 33824339, 2021). "In the present study, we demonstrate that LCN2 was expressed at significantly higher levels in patients with IBC and that LCN2 promoted tumor growth, skin invasion, and metastasis in xenograft mouse models of IBC." (PMID 34342930, 2021). "LCN2 can modulate the apoptotic process by interacting with interleukin-3 (IL-3) and IL-8 to influence tumor progression, metastasis, and prognosis in FL5.12 cells, endometrial cancer, and liver cancer." (PMID 34903175, 2021). "In line with our previous observations, only WT EC fluids were able to enhance the matrix adhesion of tumor cells, whereas EC fluids from Lcn-2−/− tumors reduced their adhesion, suggesting a reduced metastatic behavior." (PMID 33808732, 2021). "In another study, it has been reported that high lipocalin-2 expression correlated significantly with tumor differentiation (p < 0.017) and Gleason's grade." (PMID 33542838, 2021). "Lcn2 expression, which is induced by macrophage cytokine release, allows tumor cells to grow more effectively in the low nutrient CSF environment." (PMID 34276313, 2021). "We also revealed that intracellular control of LCN2 would recover the effects of FA on cell proliferation, cell cycle and tumor formation in vitro and vivo." (PMID 33659047, 2021). "In contrast, Lcn-2−/− MΦ cells present an iron-sequestering phenotype with high intracellular iron, while Lcn-2−/− tumor cells have only low iron levels." (PMID 33808732, 2021). "Combined with the previous studies, there is every reason to believe the tumor-promoter effects of LCN2 on DPC." (PMID 33407508, 2021). "Although the iron-load of Lcn-2 in defining its biological activity was described in a variety of studies, we now provide mechanistic details explaining its pro-tumor characteristics." (PMID 34069743, 2021). "After BMT and subsequent tumor implantation, we observed a decrease in daily cumulative food intake and a trend toward decreased total food intake for Lcn2-KO mice receiving Lcn2-replete bone marrow." (PMID 33824339, 2021). "Our findings support that LCN2 promotes IBC tumor aggressiveness and offer a new potential therapeutic target for IBC." (PMID 34342930, 2021).
tumor (continued). "The expression of LCN2 is significantly contributed by the regulatory T cells of the tumor microenvironment." (PMID 34588926, 2021). "This was associated with reduced pancreatic fibro-inflammation, PanIN formation, and prolonged survival, indicating a tumor-promoting role of LCN2 in PDAC." (PMID 34680216, 2021). "LCN2 expression is upregulated in many kinds of cancers and is likely involved in multiple tumorigenic processes including tumor initiation, progression, and metastasis." (PMID 34903175, 2021). "In mice bearing PDX line #5, treatment with the LCN2-neutralizing antibody alone had little effect on tumor growth, whereas the combination treatment achieved a greater anti-tumor effect than sorafenib treatment alone." (PMID 34921145, 2021). "Since collagen I and fibronectin are part of the lung matrix, we performed an adhesion assay of PyMT tumor cells stimulated with either WT or Lcn-2−/− EC fluids to determine the metastatic potential." (PMID 33808732, 2021). "LCN2 is recognized to be significantly correlated with cell differentiation and tumour invasion in ESCC." (PMID 34601488, 2021). "First, we measured the actual amount of intracellular iron in tumor cells from WT and Lcn-2−/− PyMT tumors." (PMID 33808732, 2021). "Data mining of the publicly available GSE data sets using the GEOQuery package for GNU R from the CRAN archive showed that both FPN and Lcn-2 are elevated in tumor stroma compared to the stroma of the healthy breast." (PMID 33808732, 2021). "Where PKP3 expression is decreased p38β is capable of regulating LCN2 leading to an increase in tumour invasion and metastasis." (PMID 34174910, 2021). "At the same time, based on the HPA database, the protein levels of LCN2 gene in tumor tissues were found to be significantly higher than that in normal tissues." (PMID 35111677, 2021). "Except for that, the study showed how overexpression of LCN2 enhances tumor cell migration and invasion, and, conversely, its knockdown in human cell lines suppressed their migration and invasion, both in vitro and in vivo." (PMID 33799862, 2021). "Some in vitro and in vivo studies in the literature support the role of LCN2 as a tumor promoter, but the difference is that in most of the current studies, LCN2 is generally considered to be a protective factor in CRC." (PMID 35111677, 2021). "Previous research, done by the same laboratory, also classifies LCN2 as a tumor suppressor since is seems to diminish proliferation and invasion of HCC cells through the blockade of JNK and PI3K/AKT signaling." (PMID 33799862, 2021). "Apoptotic tumor cells induced the polarization of macrophages toward the alternative M2 phenotype and stimulated expression of iron-bound Lcn-2." (PMID 34829813, 2021). "Since EMT is a critical point in tumor invasion, this finding presents LCN2 as a metastasis suppressor, and even makes it a potentially good therapeutic target." (PMID 33799862, 2021). "Another iron transport protein that was described to play a crucial role in tumor development is Lcn-2, which belongs to the lipocalin superfamily of carrier proteins." (PMID 33808732, 2021). "Recently, we provided evidence that the iron-binding capacity of Lcn-2 defines its pro-tumor characteristics in ccRCC." (PMID 34069743, 2021). "The majority of studies suggest LCN2 as a tumor promoter, while some studies show that increased LCN2 levels correlate with reduced tumor growth in certain cancer types." (PMID 34626204, 2021). "Iron-loaded Lcn-2 promoted RCC tumor growth and progression, whereas the iron-free form of Lcn-2 showed rather anti-tumoral activity, while mechanistic details on Lcn-2 signaling still remain obscure." (PMID 34069743, 2021). "The expression of LCN2 and the level of FA in tumor tissues and corresponding adjacent tissues of HCC patients were also detected." (PMID 33659047, 2021).
tumor (continued). "To identify potential mechanisms and pathways involved in suppression of tumor growth and skin invasion in LCN2‐silenced cells, we used reverse‐phase proteomics assay (RPPA) profiling to compare control and LCN2‐silenced SUM149 cells." (PMID 34342930, 2021). "Lcn-2−/− tumor cells present overall less aggressive tumoral capacity than their WT counterparts, showing less proliferation, migration, and matrix adhesion." (PMID 33808732, 2021). "In contrast, Lcn-2−/− tumor cells accumulated less iron than their wildtype counterparts, translating into a low migratory and proliferative capacity of Lcn-2−/− tumor cells in a 3D tumor spheroid model in vitro." (PMID 33808732, 2021). "To address this, we pair-fed tumor-bearing Lcn2-KO mice to their tumor-bearing WT counterparts, and observed equivalent skeletal and cardiac tissue mass at the end of the study." (PMID 33824339, 2021). "We observed a progressively increasing amount of Lcn-2 expression from day 1 to day 3 after tumor spheroid infiltration." (PMID 33808732, 2021). "Our results revealed that the level of LCN2 in tumor tissues was higher than in corresponding adjacent tissues but the level of FA in tumor tissues was lower than in adjacent tissues." (PMID 33659047, 2021). "Clinico‐pathological characteristics of tumor samples from patients with IBC or non‐IBC according to LCN2 expression." (PMID 34342930, 2021). "In compliance with our RNA-seq data of cell lines, the LCN2 transcript is elevated significantly (p = 0.0001) in the 4T1.2 primary tumor compared to the 4T1 primary tumor in the metastatic mouse model." (PMID 34072157, 2021). "To investigate the effects of LCN2 on tumor growth and skin invasion, key characteristics of IBC tumors, we injected SUM149 control or LCN2‐silenced cells into the cleared mammary fat pad of SCID/Beige mice." (PMID 34342930, 2021). "A clear correlation between LCN2 levels and tumor grade was found in in breast and thyroid cancers, whereas the opposite was suggested in ovarian and pancreatic cancers." (PMID 33287315, 2020). "We also discuss the biological and molecular consequences of LCN2 dysregulation in many tumor types, and we explain how its interaction with MMP-9 promotes cancer cell growth and metastasis." (PMID 32575507, 2020). "The biological function of LCN2 was proved to be involved in innate immune responses and inflammation tumor microenvironment and promoted malignant development in a wide variety of cancer types." (PMID 33425761, 2020). "Together, these results identify TAM-derived lipocalin-2 as a promising therapeutic target for inhibiting the tumor-supporting functions of TAM." (PMID 33679721, 2020). "In the current study, we found that acute ischemic stroke induced increased expression of LCN2 in the tumor." (PMID 32153594, 2020). "Next, we confirmed the upregulation of LCN2 expression in the tumor using immunofluorescence staining." (PMID 32153594, 2020). "Together, these results demonstrate that acute ischemic stroke induces upregulation of the mRNA level of LCN2 and an immunosuppressive cytokine production in the tumor." (PMID 32153594, 2020). "We also observed that the increased LCN2 in the tumor were mostly derived from those recruited PMN-MDSCs in the tumor." (PMID 32153594, 2020). "Nonetheless, there are more data (from cell lines, mouse models, and humans) that identify LCN2 as a tumor-promoter molecule." (PMID 32575507, 2020). "An overall significantly elevated positive signal for LCN-2 protein was observed in tumour tissue compared with healthy control tissue by using immunofluorescence staining (left)." (PMID 31772326, 2020). "Specifically, in mice exposed to P80 for 4 weeks, another study reported the lower expression of mucin-2 with an increase of lipocalin-2 (LCN2), LPS, and flagellin, associated with a higher tumor incidence." (PMID 33260947, 2020).
tumor (continued). "Both immunofluorescence staining and flow cytometry analysis revealed that increased expression of LCN2 was mainly derived from the polymorphonuclear myeloid derived suppressor cells (PMN-MDSCs) in the tumor." (PMID 32153594, 2020). "In BRCA, the level of LCN2 expression negatively correlated with tumor purity (r = −0.219, P = 3.17e-12), and positively correlated with B cells (r = 0.074, P = 2.08e-02), neutrophils (r = −0.127, P = 8.14e-05), and dendritic cells (r = 0.134, P = 3.27e-05)." (PMID 33425761, 2020). "LCN-2 protein was found overexpressed in tumour compared with adjacent healthy tissue, whereby LCN-2 was iron loaded." (PMID 31772326, 2020). "The majority of these studies agree that LCN2 upregulation promotes tumor progression and metastasis." (PMID 32575507, 2020). "In this sense, it has been shown that in different types of tumors, high LCN2 expression correlates with increased invasion, tumor formation and metastasis." (PMID 33053909, 2020). "The results indicated that LCN2 expression had significant correlations with tumor purity in 14 cancer types." (PMID 33425761, 2020). "Previous work found that IL-10, an immunosuppressive cytokine that enhances the tumor-supporting functions of macrophages, induces lipocalin-2 expression in macrophages via activation of the Jak/Stat3 signaling pathway." (PMID 33679721, 2020). "In order to test the assumption that LCN-2 transports iron to tumour cells, we generated a recombinant LCN-2 mutant protein." (PMID 31772326, 2020). "Considering that LCN2 is an important player of the tumor microenvironment and it has been suggested to be critical for cancer progression, we focused on in our following experiments." (PMID 32153594, 2020). "In general, the proposed mechanism suggests that the ternary complex (LCN2-catecholate-Fe3+) promotes tumor cell growth, prevents tumor cell apoptosis, provides resistance to hypoxic conditions, and protects tumor cells from an environment of oxidative stress." (PMID 32575507, 2020). "The results of these studies suggest that LCN2 protects tumor cells against extracellular stimuli-induced damage, thereby facilitating their survival." (PMID 33604288, 2020). "High intracellular iron levels induced by the LCN2-catecholate-Fe3+ complex suppress apoptosis of tumor cells by blocking the induction of the pro-apoptotic protein Bim." (PMID 32575507, 2020). "In breast and thyroid cancers high LCN2 expression strongly correlated with advanced tumor grade and poor prognosis, but in ovarian, pancreatic and CRC it was associated well-differentiated tumors and a good prognosis." (PMID 32328462, 2020). "A growing number of studies have identified the LCN2 gene as crucial for various tumor-related processes, including tumorigenesis, tumor progression, and tumor resistance to therapies such as radiotherapy, chemotherapy, endocrine therapy, and targeted therapy." (PMID 33604288, 2020). "As expected, we observed an increase in the levels of markers that are important for immune responses and inflammation (Saa1, Saa2, Lcn-2, Ltf, and Orosomucoid-2) and initiating and promoting tumor growth (Ighg1, Scube3, and Fgl1)." (PMID 33110211, 2020). "Although LCN2 has a very important function in tumour cells, some studies have shown that LCN2 is significantly overexpressed in kidney-related tissues and changes in LCN2 expression can be used as sensitive and specific kidney function tests." (PMID 33277533, 2020). "These TAM secrete iron, lipocalin 2 and ferritin into the tumor stroma, which increases tumor cell proliferation and metastasis." (PMID 31413815, 2019). "Deregulation of selected genes (Arg1, C7, Lcn2, Nt5e, and Tgfb1) from preinvasive lesion to overt cancers (classical tumours and PDC) was orthogonally confirmed by qPCR." (PMID 31439856, 2019). "The high-expression rate of LCN2 in tumour specimens after cisplatin treatment was 100% (5/5), while the control group and the vitamin D treatment group showed weak or no expression." (PMID 31819048, 2019).